PTPN3 (protein tyrosine phosphatase non-receptor type 3)
Diseases named in the same sentence as PTPN3 in open-access papers (continued):
Sharing a sentence is not in itself a finding about the gene and the disease.
uterine corpus endometrial carcinoma (1 paper, 2024). A endometrial carcinoma (disease) that involves the body of uterus. "There are two primary categories of PTPN3 genetic alterations observed in three distinct cases of Uterine Corpus Endometrial Carcinoma (UCEC): missense mutations and truncating mutations." (PMID 38173048, 2024).
viral infection (1 paper, 2021). "Indeed, we performed pull-down assays with PTPN3-PDZ to detect endogenous PBM-containing proteins that potentially interact with PTPN3 in cells, and that could be displaced by the PBM-HBc during viral infection." (PMID 33441627, 2021).
cancer (17 papers, 2014 to 2024). A tumor composed of atypical neoplastic, often pleomorphic cells that invade other tissues. "First, while the expression pattern in our clinical samples has been validated, the predictive significance of PTPN3 and its associations with immunotherapeutic efficacy and anti-cancer medicine sensitivity in our cohorts has yet to be proven." (PMID 38173048, 2024). "We found an association between PTPN3 expression and TMB in 8 cancers, suggesting that the overexpression of PTPN3 was positively connected with TMB in ACC, UCEC, THYM, STAD, and PAAD while negatively correlated with TMB in COAD, CESC, and SKCM." (PMID 38173048, 2024). "PTPN3 was abnormally expressed in multiple cancer types and was also strictly associated with the prognosis of cancer patients." (PMID 38173048, 2024). "The potential roles of PTPN3 mutations in human cancer are warranted for in-depth investigation in future studies." (PMID 38173048, 2024). "Our findings provide new evidence for the associations of PTPN3 with anti-cancer drug sensitivity, and targeting PTPN3 may be a practical approach to reverse cancer drug resistance." (PMID 38173048, 2024). "In addition, PTPN3 has demonstrated promise in predicting the therapeutic benefits of PD-1/PD-L1 inhibitors and the susceptibility to anti-cancer medications in the treatment of clinical cancer." (PMID 38173048, 2024). "Our study found that the total alteration rate of the PTPN3 gene was nearly 2.2% in pan-cancer, and a variety of non-synonymous mutations of PTPN3, including missense, amplification, deep deletion, splice mutation, and truncating mutation, have been detected in different cancers." (PMID 38173048, 2024). "In the present pan-cancer research, we systematically investigated and verified the PTPN3 expression pattern and its prognostic value." (PMID 38173048, 2024). "Our findings reveal that PTPN3 is significantly connected to the quantity of macrophages, T cells, and B cells in diverse cancer types." (PMID 38173048, 2024). "Our results of Kaplan–Meier OS analysis demonstrated that PTPN3 was associated with OS time in 7 cancers, DFS time in 2 cancers, DSS time in 6 cancers, and PFS time in 6 cancers." (PMID 38173048, 2024). "The Cancer Genome Atlas (TCGA) database's RNAseq data were used to examine the expression of PTPN3 in 33 different cancer types." (PMID 38173048, 2024). "Nevertheless, little is known about the biological roles of PTPN3 in drug sensitivity, immunotherapeutic effectiveness, tumor immune microenvironment, and cancer prognosis." (PMID 38173048, 2024). "To identify the primary biological process affected by PTPN3 in pan-cancer, we conducted a biological function analysis of PTPN3 in Cancer GSEA, including GO functional annotation and KEGG pathway analysis." (PMID 38173048, 2024). "Concerning the prognostic significance of PTPN3 in pan-cancer, our findings indicated that PTPN3 is a protective prognostic factor for patients with LAML, KIRC, and UCEC and a risk factor for patients with ACC, THYM, UCS, and PCPG in OS analysis." (PMID 38173048, 2024). "Taken together, our findings illustrated the prognostic value of PTPN3 in several kinds of cancers, such as ACC, KIRC, and UCEC." (PMID 38173048, 2024). "According to numerous lines of evidence, PTPN3 is abnormally elevated in several malignancies, and can promote cancer progression, metastasis, and therapy resistance." (PMID 38173048, 2024). "We further investigated the genetic alternation features of PTPN3 in pan-cancer by enrolling in the TCGA Pan-Cancer Atlas studies." (PMID 38173048, 2024). "On the other hand, TGF-β decreases PTPN3 expression and NF-κB activation in the cancer microenvironment and prevents lymphocytes from functioning biologically." (PMID 38173048, 2024).
cancer (continued). "Compared to the corresponding adjacent normal tissues of the TCGA pan-cancer data set, we found a higher PTPN3 expression in BLCA, CESC, KICH, LUSC, STAD, and UCEC, and a lower PTPN3 expression in BRCA, GBM, HNSC, KIRC, KIRP and LIHC." (PMID 38173048, 2024). "The biological analysis of pan-cancer revealed the involvement of PTPN3 in the regulation of autophagy and drug metabolism cytochrome." (PMID 38173048, 2024). "We carried out a thorough investigation in the current pan-cancer research to highlight the crucial functions that PTPN3 plays in immunological activity, immunotherapy, and cancer prognosis." (PMID 38173048, 2024). "Next, we analyze the differential expression of PTPN3 between tumor and normal tissues in the TCGA pan-cancer data set." (PMID 38173048, 2024). "Our findings highlight the importance of PTPN3 as a prognostic biomarker and predictor of immunotherapy success in various forms of cancer." (PMID 38173048, 2024). "There is a high correlation between the levels of PTPN3 expression in different cancers and infiltrating immune cells, including mast cells, B cells, regulatory T cells, CD8 + T cells, macrophages, and dendritic cells." (PMID 38173048, 2024). "Currently, several studies have demonstrated that PTPN3 is expressed differentially in malignancies and is crucial for cancer progression and prognosis." (PMID 38173048, 2024). "Despite completing extensive research to investigate and analyze the biological activities of PTPN3 in cancer progression, our current study is primarily based on bioinformatics and has certain limitations." (PMID 38173048, 2024). "PTPN3 is a potential target for new cancer immunotherapy that has a dual effect of T cell activation." (PMID 36556168, 2022). "The human protein tyrosine phosphatase non-receptor type 3 (PTPN3) is a PDZ (PSD-95/Dlg/ZO-1) domain-containing phosphatase with a tumor-suppressive or a tumor-promoting role in many cancers." (PMID 31092861, 2019). "E6 binding to PTPN3 should be favoured in HPV infected cells since E6 is highly expressed in HPV-derived cancer cells." (PMID 31092861, 2019). "In addition, we conducted a comparative analysis of the differential expression of PTPN3 in cancer samples and normal samples obtained from the GTEx database." (PMID 38173048, 2024). "Overall, PTPN3 has a variety of effects on the progression and prognosis of cancer, but the underlying processes are not well-understood." (PMID 38173048, 2024). "We further explored the prognostic significance of PTPN3 in pan-cancer." (PMID 38173048, 2024). "In this way, the body's immune response may have a significant influence on the relationship between PTPN3 expression and cancer prognosis." (PMID 38173048, 2024). "We also analyzed the expression of PTPN3 in cancer cell lines provided by the CCLE database." (PMID 38173048, 2024). "In addition, PTPN3 expression and stromal scores were negatively correlated with several cancers, including PAAD, SARC, and MESO." (PMID 38173048, 2024). "Therefore, future studies are warranted to validate the expression pattern of PTPN3 in these cancer types and should be further validated in larger cohorts with identity and modeled to remove batch effects and optimize standardized algorithms." (PMID 38173048, 2024). "Put together, PTPN3 may play diverse functions in pan-cancer and is a significant prognostic biomarker in multiple human cancers; evaluating PTPN3 expression may aid in predicting the prognosis of cancer patients, as supported by prior research." (PMID 38173048, 2024). "A comprehensive pan-cancer study may contribute to elucidating the functions of PTPN3 in immunity, immunotherapy efficacy, and cancer prognosis prediction, opening up new avenues for the discovery of novel therapeutic targets." (PMID 38173048, 2024). "Multiple lines of evidence have indicated that PTPN3 may function as a potential tumor suppressor gene in several cancers." (PMID 38173048, 2024).
cancer (continued). "Notably, GO functional annotation of PTPN3 suggested that PTPN3, across 5 cancers (CHOL, LUSC, MESO, STAD, UVM) are enriched in shared biological processes: adaptive immune response." (PMID 38173048, 2024). "In addition, immunohistochemistry (IHC) was performed to validate the expression of PTPN3 across various cancer types within our clinical cohorts." (PMID 38173048, 2024). "Our findings reveal that PTPN3 can diminish the sensitivity of certain anti-cancer medications, including paclitaxel, okadaic acid, pipamperone, and tyrothricin while increasing the sensitivity of others, including nelarabine, afatinib, lapatinib, and gefitinib." (PMID 38173048, 2024). "Then, we explored the expression of the PTPN3 in diverse cancers in the TCGA pan-cancer database." (PMID 38173048, 2024). "However, findings from several studies have indicated that PTPN3 can serve as a tumor suppressor during cancer development." (PMID 38173048, 2024). "In addition, we observed that PTPRF was co-amplified or co-deleted with PTPRK and PTPN3 in various cancers." (PMID 36341348, 2022). "PTPN3 is also often found involved in a variety of human cancers." (PMID 34835087, 2021). "In addition, we analyzed the stage-specific expressional changes of PTPN3 in pan-cancer." (PMID 38173048, 2024). "However, the fundamental mechanisms by which PTPN3 regulates tumor immunity during cancer progression are unknown and need to be validated further through research." (PMID 38173048, 2024). "In addition, we also detected an association between PTPN3 expression and MSI in 14 cancers." (PMID 38173048, 2024). "Hence, PTPN3 may play important roles in mediating targeted therapy resistance in human cancers, and monitoring PTPN3 expression may facilitate choosing the most effective therapy strategy for individual patients." (PMID 38173048, 2024). "Moreover, our findings indicate that PTPN3 was upregulated in later clinical stages in ACC and COAD, while it was significantly downregulated in later stages in KIRC and TGCT, suggesting that monitoring PTPN3 expression may predict cancer progression in clinical settings." (PMID 38173048, 2024). "Among 33 cancer types, we found that PTPN3 is connected with TMB in 8 cancer types and MSI in 14 cancer types, indicating the promising potential of PTPN3 as a predictive biomarker in immunotherapy efficacy." (PMID 38173048, 2024). "The expression of PTPN3 exhibited a substantial correlation with many immune-related biomolecules and the expression of TMB and MSI in multiple types of cancer." (PMID 38173048, 2024). "Furthermore, PTPN3 appears to have an important role in modifying the tumor immune microenvironment, highlighting its potential as a promising biomarker for prognosis prediction, immunotherapeutic efficacy evaluation, and identification of immune-related characteristics in diverse cancer types." (PMID 38173048, 2024). "It was revealed that several top up‐regulated genes such as KANK1, GALNT14, TMEM98, and PTPN3 and top down‐regulated genes such as PITX2, SNCA, and EPHA7 play key roles in cancer progression and chemotherapy response." (PMID 37937323, 2023). "The importance of protein tyrosine phosphatase non-receptor type 3 (PTPN3) in controlling multifaceted tumor cell behaviors throughout cancer development has received widespread attention." (PMID 38173048, 2024). "Comprehensive pan-cancer studies that explicitly target PTPN3 have not yet been conducted, and the precise roles that PTPN3 plays in modifying the tumor immune milieu and how that affects immunotherapy have not been thoroughly examined in scientific literature." (PMID 38173048, 2024). "The human protein tyrosine phosphatase non-receptor type 3 (PTPN3) is a phosphatase containing a PDZ (PSD-95/Dlg/ZO-1) domain that has been found to play both tumor-suppressive and tumor-promoting roles in various cancers, despite limited knowledge of its cellular partners and signaling functions." (PMID 37200868, 2023).
tumor (16 papers, 2008 to 2025). "Using Spearman's rank correlation coefficient, the relationships between PTPN3 expression and tumor mutation burden (TMB) and microsatellite instability (MSI) were evaluated." (PMID 38173048, 2024). "PTPN3 has been implicated in various tumor studies as an immune system regulator and as an immunotherapy target." (PMID 35910196, 2022). "The investigation of PTPN3's probable role in the tumor immune microenvironment was demonstrated by the application of CIBERSORT, ESTIMATE algorithms, and the TISIDB database." (PMID 38173048, 2024). "This highlighted the possible function of PTPN3 in mediating the tumor immune microenvironment and immunotherapy effectiveness." (PMID 38173048, 2024). "PTPN3 is a PDZ domain-containing phosphatase that has been demonstrated to function as a tumor suppressor or, conversely, as an oncoprotein in a context-dependent manner." (PMID 31092861, 2019). "In a recent report, PTPN3, a protein tyrosine phosphatase which acts as a tumor suppressor, was shown to enhance TβRI stability, independently of its catalytic activity." (PMID 31450767, 2019). "After 35 days, immunohistochemical (IHC) staining of tumour tissues showed that the expression of PTPN3 was significantly decreased in shPTPN3 stably transfected tumours." (PMID 27833130, 2016). "Hence, illustrating the relationship between PTPN3 and tumor immune microenvironment is of great importance." (PMID 38173048, 2024). "Hence, more in-depth studies are needed to clarify the mechanism and biological roles of PTPN3 in tumor immunity." (PMID 38173048, 2024). "PTPN3 was initially regarded as a potential tumor suppressor in colorectal cancer (CRC)." (PMID 38173048, 2024). "Above all, PTPN3 may have a significant role in controlling the tumor immune microenvironment, cytokine–cytokine receptor interaction, and antigen processing and presentation in a variety of malignancies." (PMID 38173048, 2024). "Although PTPN3 is closely related to the activation and infiltration of immune cells, its relationship with tumor immunotherapy is still largely unknown, with a great development prospect." (PMID 38173048, 2024). "More recently, protein tyrosine phosphatase non-receptor 3 (PTPN3) was reported to be frequently mutated in iCCA and associated with tumor recurrence." (PMID 31450767, 2019). "In the context of tumor immunity, PTPN family members (PTPN6, PTPN3, PTPN2, PTPN1) shape the tumor microenvironment by regulating the development and function of immune cells, thereby influencing tumor progression and the efficacy of immunotherapy." (PMID 40570022, 2025). "Previous studies reported that several PTPs such as PTPN1, PTPN3, and PTPN6 have oncogenic properties but other PTPs including PTPN12 have tumor suppressor features." (PMID 22394684, 2012). "In clear cell renal cell carcinoma, PTPN3 and PTPN13 act as tumor suppressors by inactivating the AKT signaling pathway, whereas PTPN12 restrains the proliferation of renal cell carcinoma by inhibiting PI3K/mechanistic target of rapamycin (mTOR) pathway activity." (PMID 35957898, 2022). "Besides, the specific process by which PTPN3 regulates the tumor immune microenvironment remains largely unknown, and the potential role of PTPN3 in modulating tumor immunity has not been investigated through in vivo and in vitro research." (PMID 38173048, 2024). "In our research, the results indicated that PTPN3, PTPN4, PTPN5 expression in normal tissues was lower than in PAAD tissues, but the tumor stage of PAAD patients did not affect the expression." (PMID 35154122, 2022).
infection (2 papers, 2016 to 2021). The state of being infected such as from the introduction of a foreign agent such as serum, vaccine, antigenic substance or organism. "In conclusion, during infection, the virus may target endogenous proteins for a direct and specific action as PTPN3 on encapsidation, but also for a more general perturbation of cellular homeostasis in its favor." (PMID 33441627, 2021). "Thus, the holdup assay enabled us to identify new host proteins potentially targeted by HBc during infection in addition to PTPN3 and GIPC1." (PMID 33441627, 2021). "We identified a pool of human PBM-containing proteins that might interact with PTPN3 in cells and that could be in competition with the HBc PBM during infection, and we also identified potential cellular partners of HBc through PDZ-PBM interactions." (PMID 33441627, 2021).
neurodegenerative disease (1 paper, 2023). A disorder of the central nervous system characterized by gradual and progressive loss of neural tissue and neurologic function. "PTPN3 is a potential immune checkpoint inhibitor target that may mediate T cells, while PTPN5 and PTPN7 can specifically inactivate MAPKs, so the developed inhibitors may have therapeutic potential for treating neurodegenerative diseases in AML patients." (PMID 37884566, 2023).
PTPN3 also shares sentences with these, for which no sentence is quoted: colon carcinoma (3 papers); Alzheimer disease (1); Anxiety (1); Arthritis (1); basal cell carcinoma (1); bladder urothelial carcinoma (1); breast tumors (1); cervical cancer (1); childhood asthma (1); colorectal adenocarcinoma (1); deafness (1); diabetes (1); endometrial cancer (1); epidermodysplasia verruciformis (1); essential tremor (1); glioma (1); leukemia (1); lung adenocarcinoma (1); lung squamous cell carcinoma (1); metastatic tumors (1); skin cancer (1); skin cutaneous melanoma (1); triple-negative breast carcinoma (1).